E2F1 (E2F transcription factor 1)
Diseases named in the same sentence as E2F1 in open-access papers (continued):
Sharing a sentence is not in itself a finding about the gene and the disease.
esophageal cancer (4 papers, 2017 to 2022). A primary or metastatic malignant neoplasm involving the esophagus. "Additionally, it was reported that the expression of E2F1 was associated with prognosis in esophageal cancer, and it might be a candidate target molecule for chemosensitivity of esophageal cancer." (PMID 29136005, 2017). "Also, in the context of esophageal cancer cells, it has been shown that cisplatin-induced E2F1 transactivates miR-203 by directly binding to its promoter." (PMID 32760222, 2020). "Another study identified a detailed E2F transcription factor 1 (E2F1)‐dependent mechanism by which inhibitor of DNA binding 1 (Id1) increases the expression of TS and insulin‐like growth factor 2 (IGF2) to promote esophageal cancer chemoresistance." (PMID 34766149, 2021).
Fanconi anaemia (4 papers, 2018 to 2025). "YAP depletion reduced the expression of the Fanconi anaemia (FA) pathway components required for DNA repair and their transcriptional regulator E2F1." (PMID 29928579, 2018).
gallbladder cancer (4 papers, 2020 to 2025). "Under glucose deficiency conditions, the hKIS/p27/E2F1 axis regulates STMN1 expression and gallbladder carcinoma cell migration and invasion." (PMID 35186166, 2022). "Additionally, KPNA2 promotes gallbladder cancer progression by regulating the nuclear localization of E2F1 and E2F7." (PMID 40830912, 2025). "Findings obtained from a previous study suggest that E2F1 and E2F7 have different regulatory effects on KPNA2 to promote the development of gallbladder cancer." (PMID 33489876, 2020). "Moreover, KPNA2 promotes tumor development through the nuclear localization of E2F1 and E2F7 in gallbladder cancer." (PMID 34903711, 2021).
gastric adenocarcinoma (4 papers, 2014 to 2021). "Results showed that expressions of miR-23b were significantly down-regulated in numerous stomach adenocarcinoma samples compared with normal counterparts, whereas those of Notch2 receptor, E2F1, and Ets1 mRNAs were up-regulated." (PMID 26041881, 2015). "Levels of miR-23b were lower in stomach adenocarcinoma specimens than in their corresponding normal tissue counterparts, but those of Notch2 receptor, E2F1, and Ets1 mRNAs were higher." (PMID 26041881, 2015). "Levels of miR-23b in stomach adenocarcinoma samples were down-regulated, whereas those of Notch2 receptor, v-ets erythroblastosis virus E26 oncogene homolog 1 (Ets1), and E2F1 transcripts were up-regulated." (PMID 26041881, 2015). "The relative miR-23b levels were inversely proportional to the expressions of Notch2 receptor, E2F1, and Ets1 mRNAs in stomach adenocarcinoma specimens." (PMID 26041881, 2015). "To confirm physiological binding, we performed reciprocal immunoprecipitation assays in lysates from the E2F1 stably expressing gastric adenocarcinoma cells and confirmed interaction between endogenous E2F1 and MRP." (PMID 25466554, 2014). "In summary, we demonstrated that upregulation of E2F1 significantly inhibited the sensitivity of SGC7901/DDP gastric adenocarcinoma cells to anticancer drugs, and decreased the percentage of apoptotic cells." (PMID 25466554, 2014). "Therefore, the relation of the expression of c-MET, e2f-1 and Ki-67 with the profiles of clinicopathological parameters and prognosis in the patients with gastric adenocarcinoma (GC) would be investigated in this study of ours." (PMID 24393368, 2014). "Upregulation of E2F1 in gastric adenocarcinoma cells potentiated S phase arrest of the cell cycle." (PMID 25466554, 2014).
Insulin resistance (4 papers, 2017 to 2024). Increased resistance towards insulin, that is, diminished effectiveness of insulin in reducing blood glucose levels. "At the whole-body level, E2F1 mRNA expression in human VAT correlates with insulin resistance, circulating IL-6, leptin, and FFA levels." (PMID 36231008, 2022). "E2f1 mRNA and protein levels are increased in the visceral white adipose tissue of obese human subjects and positively correlated with insulin resistance and circulating free-fatty acids." (PMID 29176962, 2017). "However, the contribution of E2F1 to the inflammation of white adipose tissue during insulin resistance remains to be explored." (PMID 29176962, 2017).
liposarcoma (4 papers, 2015 to 2024). A usually painless malignant tumor that arises from adipose tissue. "It has been reported that high E2F1 or E2F4 activity in liposarcoma patients is associated with unfavorable prognosis, with the core target gene sets of E2F1 containing 116 genes and the core target gene sets of E2F4 containing 199 genes, among which only 21 are shared." (PMID 34532281, 2021). "A representative heatmap shows the overexpression of the genes in the E2F1/NFY signature in dedifferentiated liposarcoma compared to normal adipose tissue." (PMID 26039627, 2015). "Additionally, it has also been reported that HMGA1 regulated drug resistance in liposarcomas, through a mechanism involving E2F1." (PMID 38758230, 2024).
mantle cell lymphoma (4 papers, 2008 to 2024). Mantle cell lymphoma is a rare form of malignant non-Hodgkin lymphoma affecting B lymphocytes in the lymph nodes in a region called the ``mantle zone''. "Furthermore, PD-0332991 was also shown to downregulate E2F1 in mantle cell lymphoma." (PMID 25136922, 2014). "An in vitro study in mantle cell lymphoma revealed that the CDK4/6 inhibitor, PD-0332991, suppressed E2F1 expression." (PMID 25136922, 2014).
pancreatic adenocarcinoma (4 papers, 2015 to 2025). "Moreover, a direct correlation between E2F1 and cell proliferation, as well as an inverse association between E2F1 and disease-associated survival has been observed in pancreatic adenocarcinoma." (PMID 29596435, 2018). "In this study, we found the role of BCL2L1 and E2F1 in the process of pancreatic adenocarcinoma, which was in line with previous researches." (PMID 29596435, 2018). "Finally, 8 differentially expressed genes (ERLIN1, HMGA2, FAM110B, EGFR, MCM2, BCL2L1, E2F1 and RAC1) were considered to be significantly negatively associated with survival (P < 0.05) time of pancreatic adenocarcinoma patients." (PMID 29596435, 2018). "According to the KEGG pathway analysis, we found that several tumor differentiation related genes (such as BCL2L1, E2F1, RAC1 and STAT1) were remarkably enriched in pancreatic adenocarcinoma signaling pathway." (PMID 29596435, 2018). "Significantly, we also found the roles of BCL2L1, E2F1 and RAC1 in tumor differentiation and survival prediction of pancreatic adenocarcinoma." (PMID 29596435, 2018). "Herein, we found that BCL2L1, E2F1, RAC1 and STAT1 were expressed in pancreatic adenocarcinoma, which was consistent with previous reports." (PMID 29596435, 2018). "A negative correlation between miR-126 and E2F1 expression has also been found in pancreatic adenocarcinoma." (PMID 39796183, 2025).
Parkinson disease (4 papers, 2008 to 2025). A progressive degenerative disorder of the central nervous system characterized by loss of dopamine producing neurons in the substantia nigra and the presence of Lewy bodies in the substantia nigra and locus coeruleus. "E2F1, as a key cell cycle regulator, has been shown to play essential roles in a range of neurological disorders like stroke, Parkinson's, and Alzheimer's, controlling multiple signalling pathways, including cell apoptosis and inflammatory responses." (PMID 39968698, 2025). "Additionally, E2F1 has been found to play crucial roles in various neurological disorders, encompassing stroke, Parkinson's disease, and Alzheimer's disease." (PMID 39968698, 2025).
pulmonary fibrosis (4 papers, 2021 to 2025). Chronic progressive interstitial lung disorder characterized by the replacement of the lung tissue by connective tissue, leading to progressive dyspnea, respiratory failure, or right heart failure. "Herein, we explored the molecular mechanism by which microRNA‐205‐5p (miR‐205‐5p) affects the autophagy of alveolar macrophages (AMs) and pulmonary fibrosis in mice with silicosis through the E2F transcription factor 1 (E2F1)/S‐phase kinase‐associated protein 2 (SKP2)/Beclin1 axis." (PMID 34428336, 2021). "The transcription factor E2F1 affects the progression of the cell cycle, plays an important role in the excessive increase of lung fibroblasts in pulmonary fibrosis." (PMID 40615041, 2025). "R analysis showed that E2F1 gene was highly expressed in pulmonary fibrosis in the microarray data set GSE110711." (PMID 34428336, 2021). "Our findings revealed that miR‐205‐5p impaired pulmonary fibrosis and E2F1/SKP2/Beclin1 axis was responsible for the role of miR‐205‐5p in such process." (PMID 34428336, 2021). "Therefore, the afore‐mentioned findings revealed that miR‐205‐5p inhibited pulmonary fibrosis via the E2F1/SKP2/Beclin1 axis." (PMID 34428336, 2021). "Additionally, miR‐205‐5p agomir suppressed the pulmonary fibrosis in mice with silicosis, while Lenti‐E2F1, Lenti‐SKP2 or siBeclin1 counteracted this suppression." (PMID 34428336, 2021). "As SKP2 has been reported to mediate the ubiquitination of Beclin1,21 we speculated the involvement of miR‐205‐5p in autophagy and pulmonary fibrosis through mediating the E2F1/SKP2/Beclin1 axis." (PMID 34428336, 2021). "Additionally, miR‐205‐5p overexpression increased autophagy and reduced the pulmonary fibrosis, while overexpression of E2F1 or SKP2 or inhibition of Beclin1 could annul this effect." (PMID 34428336, 2021). "The latest research showed that E2F1 affected TGF-β1-induced pulmonary fibrosis and epithelial-mesenchymal transition (EMT) in BEAS-2B cells through the miR-106b-5p/E2F1/SIX1 signaling pathway." (PMID 37128280, 2023). "The current study elucidated that miR‐205‐5p targeted E2F1, thereby inhibiting SKP2‐mediated Beclin1 ubiquitination to promote macrophage autophagy and inhibit pulmonary fibrosis in mice with silicosis." (PMID 34428336, 2021). "We silenced or overexpressed miR‐205‐5p, E2F1, SKP2 and Beclin1 to investigate their potential roles in pulmonary fibrosis in vivo and autophagy in vitro." (PMID 34428336, 2021).
rheumatoid arthritis (4 papers, 2021 to 2025). A chronic, systemic autoimmune disorder characterized by inflammation in the synovial membranes and articular surfaces. "Although the underlying mechanism is elusive, our ChIPEA suggested that LEF suppresses tumor growth by activating TLE3 and inactivating RELA and E2F1, possibly via the same mechanisms involved in rheumatoid arthritis treatment." (PMID 35073843, 2022).
sarcoma (4 papers, 2015 to 2025). A usually aggressive malignant neoplasm of the soft tissue or bone. "In five independent sarcoma datasets, the E2F1/NFYB signature is significantly associated with signatures (concepts) consisting of genes that are overexpressed in cancer compared to normal tissue." (PMID 26039627, 2015). "Furthermore, in silico analysis of this subset of co-regulated genes suggests that the NFYB-dependent E2F1 program is upregulated and linked with various types of sarcoma when compared to corresponding normal tissue." (PMID 26039627, 2015). "Mirroring MNK1/2 silencing, ETC-168 treatment strongly blocks eIF4E phosphorylation and represses expression of sarcoma-driving onco-proteins including E2F1, FOXM1, and WEE1." (PMID 33564073, 2021). "An Oncomine query with the E2F1/NFYB signature revealed sarcoma as the most significant cancer type in tumor versus normal analysis." (PMID 26039627, 2015). "The Oncomine analysis further indicated lower expression of the E2F1/NFYB signature in drug sensitive sarcoma cell lines compared with drug resistant lines in six independent datasets." (PMID 26039627, 2015). "Together with the data showing that NFYB is protective against E2F1-mediated apoptosis, these results suggest that the NFYB-dependent E2F1 transcriptional program we defined may be involved in the oncogenesis or maintenance of sarcomas." (PMID 26039627, 2015). "Further enhancing this idea is the fact that E2F1 target genes induced in an NFYB-independent manner do not show this association with sarcoma." (PMID 26039627, 2015). "Our results showing NFYB to be protective against E2F1 mediated apoptosis moreover suggest this NFYB/E2F1 regulated gene set may be involved in the development or survival of sarcoma cells." (PMID 26039627, 2015). "Finally, our cancer vs normal analysis using a set of genes jointly induced by E2F1 and NFYB demonstrated most significant overexpression in sarcoma." (PMID 26039627, 2015).
thyroid tumor (4 papers, 2013 to 2023). A benign or malignant neoplasm affecting the thyroid gland. "Molecular analyses in these mice revealed the activation of the cyclin 1–cyclin-dependent kinase-4–transcription factor E2F1 pathway, known to be associated with thyroid tumour cell proliferation." (PMID 24683474, 2013).
Type 2 Diabetes (4 papers, 2020 to 2023). "It has been demonstrated that E2F1 essentially involved in hyperlipidemia and hyperglycaemia during resistance to insulin and abnormally increased in type 2 diabetes." (PMID 32884568, 2020). "The copy numbers of studies for risky genes in type-2 diabetes patients have shown that epidermal growth factor receptor (EGFR), E2F transcription factor 1 (E2F1), protein phosphatase 1 regulatory subunit 3A (PPP1R3A), human leukocyte antigen (HLA), and tetraspanin 8 (TSPAN8) are important." (PMID 34563047, 2021).
uveal melanoma (4 papers, 2019 to 2021). A melanoma derived from melanocytes of the uveal tract. "The E2F1 targets pathway was involved in the BAP1-mediated cell cycle progression of uveal melanoma cells." (PMID 34434692, 2021). "In uveal melanoma cells, BAP1 knockdown causes G1 arrest most likely through HCF1-mediated effects that involve histone deubiquitination and effects on E2F1-dependent transcription." (PMID 30669483, 2019).
ACTHomas (3 papers, 2018 to 2022). "Cell cycle proteins cyclin E, p27, Rb, and E2F1 exhibit different levels of lineage-specific expression patterns in embryonic cells, adult normal pituitary, and corticotroph adenoma." (PMID 30147673, 2018). "Moreover, corticotroph-specific EGFR overexpression leads to ACTHomas mediated via E2F1 activation." (PMID 33266265, 2020).
adenoma (3 papers, 2021 to 2022). A neoplasm arising from the epithelium. "Compared to MYC or E2F-1 transgenic mice, double transgenic animals also showed potential cooperation between MYC and E2F-1 oncogenes, featuring a high frequency of β-catenin mutational activation and nuclear accumulation in both adenomas and carcinomas." (PMID 34771745, 2021).
astrocytomas (3 papers, 2018 to 2022). "In addition, it was shown that an increased expression of the transcription factor E2F1 and glycogen synthase kinase-3B correlated with the level of LSH in astrocytomas and GBM, also leading to an increased progression of the disease." (PMID 36425564, 2022).
Autoimmunity (3 papers, 2015 to 2025). The occurrence of an immune reaction against the organism's own cells or tissues. "It has been suggested that E2F1 may have effects on autoimmunity at the molecular level in vivo." (PMID 39902022, 2025). "It was found that autoimmunity does not occur in mice with E2F1 deficiency." (PMID 39902022, 2025). "Although E2F1 has been shown to be a cell cycle progressor in many cellular contexts, studies show that in murine CD8+ T cells, E2F1 and E2F2 redundantly restrict cell cycle progression and proliferation following sub-threshold antigen stimulation, and mice are more prone to autoimmunity." (PMID 26393659, 2015).
Bladder Urothelial Carcinoma (3 papers, 2015 to 2023). "E2F1 promotes the invasiveness of urothelial bladder carcinoma 3,4,9,10." (PMID 32863950, 2020).
cervical squamous cell carcinoma (3 papers, 2020 to 2022). A squamous cell carcinoma arising from the cervical epithelium. "CircZFR acted as an activator of Rb-E2F1 signaling, which promoted the G1/S transition, cell proliferation, migration, and invasion of squamous cervical cancer." (PMID 33516252, 2021). "E2F1/2/7/8 were highly expressed in cervical squamous cell carcinoma tissues, with no detectable expression found in normal tissues." (PMID 33061852, 2020).
colon adenocarcinoma (3 papers, 2022 to 2023). "E2F1 has been shown to promote the progression of colon adenocarcinoma through the up-regulation of lncRNA MNX1-AS1, and E2F1 can bind to the promoter region of MNX1-AS1." (PMID 35152841, 2022).
deafness (3 papers, 2018 to 2020). An inherited or acquired condition characterized by the complete loss of the ability to hear from one or both ears. "E2F1 is an important pro-apoptotic TF, and under some mitochondrial stress, it engages apoptotic signals to cause deafness." (PMID 29929553, 2018). "We also identified E2f1, which is linked to maternally inherited deafness originating from aberrant methylation and an increase in this pro-apoptotic TF31." (PMID 30478432, 2018).
fibrosarcoma (3 papers, 2016 to 2025). A malignant mesenchymal fibroblastic neoplasm affecting the soft tissue and bone. "interestingly, we observed that SLC7A11 was upregulated at both the mRNA and protein levels upon E2F1 overexpression in HT1080 (fibrosarcoma) cells." (PMID 36778475, 2023).
Gestational Diabetes Mellitus (3 papers, 2019 to 2020). "One study showed that upregulation of miR-330-3p reduces the expression of CDC42 and E2F1 in patients with gestational diabetes (GDM), resulting in impaired β-cell proliferation." (PMID 33149760, 2020). "One study showed that up-regulation of miR-330-3p reduces expression of Cdc42 and E2F1 leading to impaired β cell proliferation via transferring from the plasma membrane to the cytoplasm of β cells in gestational diabetes mellitus (GDM)." (PMID 30621321, 2019).